MMP2 (matrix metallopeptidase 2)
Diseases named in the same sentence as MMP2 in open-access papers (continued):
Sharing a sentence is not in itself a finding about the gene and the disease.
tumor (continued). "Nevertheless, the secretion of other molecules implicated in the regulation of tumor angiogenesis in CM (e.g., MMP-2, MMP-3, MMP-8) were significantly reduced in Spry1KO Mel 593 clones." (PMID 39953610, 2025). "Among these, MMP-14 emerged as being particularly relevant, given its association with disease status and risk of tumor recurrence, as well as its well-documented ability to activate other MMPs, including MMP-2 and MMP-9." (PMID 40869275, 2025). "This vascular phenotype was associated with increased tumor cell apoptosis and prolonged survival in tumor-bearing mice, indicating that MMP-2 is essential for functional angiogenesis in GBM." (PMID 40265458, 2025). "High MMP-2 expression is strongly linked to advanced tumor stage, lymph node involvement, and distant metastasis." (PMID 41154590, 2025). "Regarding tumor size and grade, positive MMP-2 expression was closely associated with MRI signal uniformity." (PMID 39684754, 2024). "E-cadherin and matrix metalloproteinase-2 (MMP-2) are reported to be closely associated with tumor invasion." (PMID 39000339, 2024). "The innovative approach involved conjugating PEG to PLA through the intermediary peptide PVGLIG, a sequence recognized for its specificity to be cleaved by matrix metalloproteinase-2 (MMP-2), a tumor-associated enzyme." (PMID 38675124, 2024). "SDC2 on this subgroup can interact with MMP2 on tumor-associated fibroblasts and endothelial cells, promoting tumor growth and metastasis." (PMID 39308672, 2024). "PEG-PLA linked through a cleavable synthetic peptide sequence, PVGLIG, were prepared for targeting the tumor-associated MMP-2 enzyme, allowing a seven-fold higher release rate than when exposed to the MMP-2 enzyme at physiological conditions." (PMID 38255485, 2024). "This is relevant because the lymph nodes are known to be acidic and high MMP2 expression has been detected in the tumour-draining lymph nodes of cancer patients." (PMID 39200132, 2024). "After matrix metalloproteinase (MMP)-2 cleavage at the tumor location, the released drugs caused modulation of the tumor immune microenvironment (TIME) and increased anticancer activity." (PMID 39409876, 2024). "FCRLA promoted the malignant biological behavior of RCC cells through the pERK1/2/‐MMP2 pathway and was associated with tumor immune microenvironment in RCC." (PMID 39108036, 2024). "Different MMPs are implicated in tumor development and some of them, essentially the gelatinase MMP-2 and MMP-9, have a role in dormant cell reactivation." (PMID 39682261, 2024). "The study of the immunodetection of metalloproteases in PC-3 tumours revealed that the combined treatment caused a decrease in MMP-2 and MMP-9; in the latter case, this was similar, although somewhat weaker, to that obtained after treatment with MIA-690." (PMID 39456984, 2024). "In fact, MMP2 upregulation has been shown to be strongly associated with tumor malignancy and metastasis." (PMID 38893093, 2024). "Among the parameters associated with tumor angiogenesis and cell invasion, only responders showed a decrease of active MMP-2 levels during maintenance with indinavir and post-therapy follow-up." (PMID 39028943, 2024). "High MMP2 expression was significantly associated with advanced tumor stages, lymph node involvement, and metastasis in CRC patients." (PMID 38978899, 2024). "In the tumor matrix, highly expressed MMP2 cleaves PDPPA-1 and high GSH concentrations cause disulfide bond cleavage, resulting in a size reduction and charge reversal, promoting the penetration of nanocarriers into tumors." (PMID 39337266, 2024). "This vaccine formulation, comprising plasmid DNA encoding chicken MMP-2, induced a robust anti-tumor response in mouse models." (PMID 39081320, 2024). "Loss of angiogenic capacity and inhibition of tumor cell motility are the outcomes of MMP-2 downregulation." (PMID 37228582, 2023).
tumor (continued). "Higher expression of MMP-2 was associated with higher invasiveness of canine OS cell lines and tumor aggressiveness." (PMID 37373007, 2023). "Tumor‐associated marker expression was significantly different among all cell types for MMP2, MMP7, MMP9, MMP12, ABHD5, ADAMTS1, AP‐1, and MGLL each with p < 0.001." (PMID 38037545, 2023). "Its activation in tumor-associated microglia/macrophages increases the adhesion/migration capacity of GBM cells through the expression of MMP-2, -9, and -14." (PMID 37108208, 2023). "Its primary receptor is TrkB, with overexpression in several tumor cells that activate MMP-2 to cause increased invasiveness and poor prognosis." (PMID 37887547, 2023). "Abnormal expression of membrane type 1‐matrix metalloproteinase (MT1‐MMP) in tumours is associated with the regulation of MMP‐2 activity." (PMID 37697969, 2023). "In the case of GBM, the MMPs of greatest interest are MMP-2 and -9, due to the close association with tumour growth and malignant progression." (PMID 36675073, 2023). "In co-cultured LC cells, G-Rh2 significantly inhibited MMP-2/9 expression, thereby converting tumor-associated macrophages (TAMs) from M2 to M1 and inhibited cancer migration." (PMID 37766868, 2023). "The inherent differences in the basal levels of exosome-associated MMP-2 present in metastatic-derived exosomes compared to primary exosomes, further suggests that the MMP-2-associated exosomes promote tumour progression." (PMID 37174066, 2023). "Meanwhile, the overexpression of FSTL1 also caused a decrease in MMP2 expression which is related to tumor metastasis." (PMID 36756161, 2023). "MMP2, a cancer-causing gene, significantly impacts the movement of cells, tumor microenvironment, and angiogenesis." (PMID 37990331, 2023). "Gene expression analysis in PM demonstrated that a high expression of TGF-β1 and MMP2 was associated with the presence of tumor-promoting M2 macrophages." (PMID 37686215, 2023). "Matrix metalloproteinases (MMPs), especially MMP2, 3, 9 and 14, derived from cancer-associated fibroblasts (CAFs) and tumour cells, are powerful TME remodelling factors, which enhance tumour invasiveness and metastasis in OSCC." (PMID 36765296, 2023). "Matrix metallopeptidase 9 (MMP9) and matrix metallopeptidase 2 (MMP2) are the most frequent metalloproteases associated with tumor angiogenesis." (PMID 37968257, 2023). "QSOX1, another PAS marker revealed here, has also been implicated in tumor cell invasion, through activation of MMP-2 and MMP-922." (PMID 36604494, 2023). "In particular, high levels of MMP-9 and MMP-2 were found to be associated with a higher tumor grade, a lesser response to chemotherapy, and a worse survival outcome." (PMID 36980765, 2023). "Proinflammatory CD80, CXCL10, anti‐inflammatory IL‐10, and the tumor‐associated markers MMP2, MMP7, MMP12, and MGLL showed lower baseline expression and were upregulated in macrophages as well." (PMID 38037545, 2023). "The results of the present study revealed that a higher serum level of MMP-2 was associated significantly with tumor staging (p = 0.043), 50% SUVmax threshold (p = 0.003), and ECOG performance status (p = 0.019)." (PMID 36013494, 2022). "Not only does MMP2 play a role in excessive ECM degradation allowing for tumor cell metastasis and invasion but MMP2 is also implicated in cancer advancement through cellular apoptosis, proliferation, and angiogenesis." (PMID 36624735, 2022). "Meanwhile, the infiltration of Tregs into tumor tissues is often associated with poor prognosis via the suppression of MMP2 in BLCA TME." (PMID 36568387, 2022).
tumor (continued). "Mechanistically, CAFs-derived TGF-β and SDF1 facilitated VM formation by inducing the expression of endothelial cells markers and the ECM remodeling-associated genes, such as VE-cadherin, MMP2, and laminin5γ2 in tumor cells." (PMID 35971182, 2022). "In the xenograft tumours, compared with the siNC control group, HBx‐expression and knockdown of B56γ in the si2R5C group upregulated the expression of p‐AKTThr308/Ser473 and tumour metastasis‐associated MMP2 and MMP9." (PMID 35811356, 2022). "MMP2, also known as gelatinase A, digests collagen IV of the basal lamina and is upregulated in many tumor cells and in tumor-associated endothelial cells." (PMID 35209039, 2022). "Taken together, we demonstrated that the HOXD11/FN1/MMP2/MMP9 axis was an underlying molecular mechanism promoting tumor invasion and metastasis via an EMT-like phenotype in PSCC." (PMID 36151071, 2022). "Recent studies have reported that HGF promotes the invasion of tumor cells associated with the up-regulation of MMP-2 and MMP-9." (PMID 36291760, 2022). "Matrix metalloproteinases 2 (MMP2) promotes immunosuppressive TME formation by reducing anti-tumor-associated immune cells (CD4+ and CD8+ T cells, NK cells, and CD103+ DCs) and increasing M2-like macrophages." (PMID 36185210, 2022). "Matrix metalloproteinase 2 (MMP-2) is implicated in numerous pathogenic processes, including tumor invasion and metastasis." (PMID 35137850, 2022). "The tumour immune environment contained high M2 macrophage infiltrate linked with MMP2, MMP14, TGFB1 and CCL2 expression, representing an immune suppressive environment." (PMID 35637530, 2022). "Matrix metalloproteinase 2 (MMP2)-sensitive PS-modified nanoparticles were developed to target Tumor-associated macrophages (TAMs) in the tumor microenvironments." (PMID 35422844, 2022). "Based on previous studies, the overexpression of MMP2 is associated with tumor differentiation, invasion, angiogenesis, and metastasis." (PMID 35681609, 2022). "A selective MMP2 inhibitor (a novel peptide CCKIGLFRWR) was linked with doxorubicin (DOX) to produce an amphiphilic peptide-drug nanoparticle which can inhibit tumor metastasis and augment treatment efficacy." (PMID 36246349, 2022). "Elevated expression of MMP-2/9 has been associated with increased metastatic potential in many tumor cells, including CRC." (PMID 35887021, 2022). "Next, we collected the co‐culture supernatant and tumor cell lysate, and detected MMP2 in the culture medium using an enzyme‐linked immunosorbent assay (ELISA)." (PMID 35901491, 2022). "The effects of GSK-3β inhibition on tumour invasion, susceptibility to gemcitabine, MMP-2 expression and FAK phosphorylation were observed in vitro as well as in tumour animal models." (PMID 36430630, 2022). "Low MMP2 expression was associated with deeper tumour infiltration (mean infiltration depth 13 ± 8mm vs. 9 ± 4mm, p=0.025), but not with any of the other clinicopathological characteristics." (PMID 35756604, 2022). "A significant association between tumor aggressiveness and increased MMP-2 and MMP-9 levels has been proved." (PMID 36079127, 2022). "CXCL5 also induced levels of MMP2 and β-catenin that are associated with matrix remodeling during tumor progression." (PMID 34831316, 2021). "In the context of tumor neoangiogenesis, the higher activity of MMP-2 and -9 was consistently associated with the release of VEGF from ECM reservoirs, contributing to the angiogenic switch." (PMID 34066355, 2021). "The high expression of MMP-2 was significantly associated with tumor differentiation (Well + Moderately 56.3% vs Poorly 81.1%; P < 0.05) and depth of invasion (pT; pT1 + pT2 55.9% vs pT3 + pT4 82.9%; P < 0.05)." (PMID 34027107, 2021). "Tumor-associated macrophages (TAMs) have been found to directly result in the degradation of ECM and promote the invasion of the tumor cells by secreting the proteolytic enzymes (MMP-2 and MMP-9) and stromal-associated proteins." (PMID 34722623, 2021).
tumor (continued). "In conclusion, high MMP-2 expression was significantly associated with tumor differentiation and depth of invasion in AEG patients." (PMID 34027107, 2021). "To our surprise, we found that Mmp2 with metalloprotease-2 as the end product, and Acta2 encoding for α2-smooth muscle actin, are also underexpressed in tumor cells." (PMID 34737944, 2021). "To evaluate the prognostic values of MMP2/9 in BC, we performed a meta-analysis for the associations between MMP2/9 overexpression in tumor cells with the clinicopathologic features and survival outcomes in BC patients." (PMID 33568081, 2021). "The result showed that the high expression of MMP-2 was significantly associated with tumor differentiation (P < 0.05) and depth of invasion (pT, P < 0.05)." (PMID 34027107, 2021). "The cancer-associated fibroblasts promote tumour invasion with matrix-metalloproteinases 2 and 9, known as MMP2 and MMP9, and the hepatocyte growth factor known as HGF." (PMID 33447887, 2021). "MMP2/9 overexpression has been associated with tumor size, metastasis, clinical stages and histological grades, all of which were well-known clinicopathological features influencing the survivals of BC patients." (PMID 33568081, 2021). "MMP2 expression was associated with tumor size, invasion and metastasis, microvessel density and VEGF expression in GC." (PMID 34972532, 2021). "Upregulation of MMP-2 is suggested to be associated with the malignant behavior of tumor cells, including in PTC." (PMID 34684168, 2021). "The 5-year survival rate for the 69 AEG patients was 40.6% and it was significantly associated with tumor differentiation (P < 0.05), pN (P < 0.01), pTNM stage (P < 0.01), MMP-2 expression (P < 0.05), and VEGF expression (P < 0.05)." (PMID 34027107, 2021). "Grp170 has also been shown to associate with matrix metalloproteinase-2 (MMP-2) thereby promoting tumor invasion." (PMID 33525518, 2021). "An increase in CD31+ endothelial-like stromal cells was described in other Mmp2-deficient tumors, suggesting that their increased presence in Mmp2-deficient tumors contributes toward tumor control." (PMID 34032639, 2021). "Based on the study of 69 AEG patients, our results showed that the high expression of MMP-2 was significantly associated with tumor differentiation and depth of invasion (pT)." (PMID 34027107, 2021). "The associations of MMP2/9 overexpression in tumor cells with overall survival (OS), disease-free survival (DFS) and recurrence-free survival (RFS) were assessed by hazard ratio (HR) and 95% confidence interval (CI)." (PMID 33568081, 2021). "Mounting research demonstrates that aberrant MMP2 expression in diversecancers is linked to tumor aggressiveness." (PMID 34837683, 2021). "We observed that the PRRX1-high tumours expressed several cancer-associated genes (e.g. MMP2/9, ZEB2, VIM)." (PMID 34496784, 2021). "MMP-2 downregulation in chicken chorioallantoic membrane models as well as MMP-2 deficiencies in mice are linked to decreased tumor angiogenesis and growth." (PMID 33810259, 2021). "The uptake of MC EVs by tumor cells caused a great increase in MMP-2 and MMP-9 mRNAs and a concomitant significant increase in uPA and uPAR, mainly in the Caco-2 cell line." (PMID 34065529, 2021). "Considering that the GAP domain was reported to inactive Rac1 or Cdc42, which is involved in tumor cell migration and associated with MMPs, we detected the Rac1 and Cdc42 activity and MMP-2/9 expression level upon Porf-2 expression." (PMID 32676454, 2020). "Tumors were excised one month after injection and, consistent with our in vitro findings, protein analyses of tumor tissues revealed that Spry1KO associated to decreased MMP-2 protein expression, and to enhanced MAPK/ERK and p38/MAPK phosphorylation." (PMID 32444628, 2020). "MMP-2 is abundant in several kinds of tumor cells and is known to be closely associated with tumor progression and metastasis." (PMID 31948442, 2020).
tumor (continued). "Doxorubicin and Trifolium pratense L. (Red clover) extract synergistically inhibited the metastasis of 4T1 to the lungs and brain by reducing cytokines (IL‐6 and IL‐8) and genes (SIRT‐1 and MMP‐2) associated with metastasis in tumor‐bearing BALB/c mice." (PMID 33133558, 2020). "Along these same lines, multiple studies reported that high levels of the MMP2 protein were linked with larger tumor size and more tumor invasion." (PMID 33203436, 2020). "While MMP-2 deficiency is associated with a reduction in the number of immature blood vessels along with reduced tumor burden, MMP-9 primarily plays a role in vascular remodeling." (PMID 32842503, 2020). "In particular, increased activity of MMP-2 and decreased expression of E-cadherin were associated with tumor growth and development." (PMID 32197606, 2020). "NF‐κB–associated proteins involved in tumour progression, such as MMP‐2, MMP‐9, uPA, VEGF, XIAP and Cyclin D1, were all decreased by imipramine." (PMID 32149465, 2020). "Our conclusion is similar to previous studies that the high expression of MMP2 in NSCLC was associated with tumor type and clinical stage and has a predictive value for low survival rates, short overall survival (OS) and disease free survival (DFS)." (PMID 33115469, 2020). "An enriched environment is linked to a decrease in the tumour proliferative pathway ERK1/2 associated with the decrease in MMP2 and 3 as well as the tumour anti-oxidative response and COX total activity." (PMID 32472095, 2020). "In pediatric cases, positive MMP-2 expression has been related to the high-risk tumor group and T-cell immunophenotype." (PMID 32751899, 2020). "In contrast to hypermethylation, hypomethylation of sulfatase 1 (SULF1) and matrix metalloproteinase 2 (MMP2) promoters was observed to be associated with the enrichment of F. nucleatum in our HNSCC tumor tissues." (PMID 33218162, 2020). "Increased MMP2 was associated with low differentiation (p = 0.022), tumor size (p = 0.032), lymph node metastasis (p < 0.001), advanced stage (p = 0.002)." (PMID 33115469, 2020). "Up-regulated MMP2 expression is often detected in solid tumor tissues and is associated with tumor metastasis in HCC." (PMID 30925583, 2019). "Many over-expressed genes in tumor-associated T cells were involved in tissue remodeling (e.g., Col1a1, Col4a1, Fn1, Lamc1, Mmp2, Mmp10, Timp3) and cell motility/adhesion (Rhoc, Itga1, Itgav)." (PMID 31477729, 2019). "The diagnostic sensitivity of TIMP-2 (79%) was higher than MMP-2 (47%) and classical tumor markers (CA 19-9 – 71% and CEA – 37%)." (PMID 30719232, 2019). "In the EMT of HCC, MMP-2 seems to be linked to HIF-1α, a known enhancer of tumor invasion and metastasis, which downregulates E-cadherin and upregulates MMP-2." (PMID 31886121, 2019). "According to our knowledge, this is the first study comparing diagnostic usefulness of MMP-2 in relation to its tissue inhibitor and classical tumor markers in PC." (PMID 30719232, 2019). "The diagnostic specificity of MMP-2 (67%) was higher than for its tissue inhibitor (37%), but lower that for classical tumor markers – CA 19-9 (97%) and CEA (98%)." (PMID 30719232, 2019). "High levels of MMP-2 are associated with tumor progression, including cancer cell proliferation, invasion, metastasis, and progression." (PMID 31393969, 2019). "In somatotroph PAs, HEPN-1 silencing is associated with aggressive tumor behavior and is found to promote invasiveness via upregulation of MMP-2 and MMP-9 in GH3 and GT1.1 cells." (PMID 32922863, 2018). "For instance, matrix metalloproteinase-2 (MMP-2) is an important enzyme in the process of extracellular matrix remodeling implicated with tumor invasion and metastasis." (PMID 29977454, 2018). "Overexpression of MMP2 seemed strikingly associated with HCC because MMP2 in the tumor is mainly responsible for the fibrogenesis." (PMID 29977454, 2018).